LEP (leptin)
Diseases named in the same sentence as LEP in open-access papers (continued):
Sharing a sentence is not in itself a finding about the gene and the disease.
Obesity (continued). "Whilst ID is the central feature of ID, obesity and altered circulating concentrations of the adipose tissue‐derived hormones adiponectin and leptin, as well as hypertriglyceridaemia, are additional features of EMS and EMS is associated with an increased risk of endocrinopathic laminitis." (PMID 38984777, 2025). "Hypothalamic endoplasmic reticulum (ER) stress contributes to leptin resistance in obesity." (PMID 40923443, 2025). "These obesity-related changes may include alterations in the leptin hormone which can stimulate POMC-expressing neurons and subsequently affect MC4R stimulation." (PMID 39542230, 2025). "The leptin resistance observed in obesity also contributes to the onset of T2D." (PMID 40227203, 2025). "However, in obesity, leptin resistance, marked by elevated circulating leptin but impaired BBB transport and receptor desensitization, blunts this neuroprotective axis, accelerating both amyloid and tau pathology." (PMID 41155642, 2025). "Sex-specific effects must also be integrated: postmenopausal women with obesity may be particularly vulnerable due to adipose and inflammatory shifts affecting leptin and resistin." (PMID 41155642, 2025). "Significantly increased levels of leptin (68.5 ± 0.35 ng/mL versus 66.73 ± 0.42 ng/mL; p = 0.012) and insulin (98.03 ± 0.54 μIU/mL versus 95.51 ± 0.47 μIU/mL; p = 0.008) suggested a strong resistance to these hormones, typical of monogenic obesity types." (PMID 40428329, 2025). "Similarly, other components of the leptin–melanocortin axis, including LEP, LEPR, POMC, PCSK1, and SIM1, have been associated with both monogenic and polygenic obesity." (PMID 41226372, 2025). "In obesity, circulating leptin levels are markedly elevated." (PMID 41463063, 2025). "Furthermore, adipokines secreted by adipose tissue—such as leptin and adiponectin—play crucial roles in linking obesity, IR, and reproductive function." (PMID 41393278, 2025). "Furthermore, previous studies have demonstrated that androgen excess can increase food intake and promote obesity by suppressing insulin and leptin signaling in the hypothalamus and upregulating the expression of pro-phagocytic genes." (PMID 40444232, 2025). "Nevertheless, other mechanisms related to obesity such as an altered hormone level, increased leptin levels or obstructive sleep apnea might also affect liquor production and absorption." (PMID 40719929, 2025). "A coculture model using two CC cell lines (HT-29 and SW480) and THP-1 cell line-derived M0 and M2-like macrophages was used to evaluate NOTCH4-GATA4-IRG1 pathway-related gene expression following treatment with obesity-related hormones (leptin, adiponectin) and itaconate derivatives." (PMID 40552282, 2025). "Consistently, SOCS3 overexpression in POMC neurons leads to leptin resistance and mild obesity." (PMID 41251447, 2025). "Similarly, obesity (BMI ≥ 30, 41.0%) contributes to mechanical joint stress and adipose-derived inflammation via adipokines like leptin, further supporting its role in arthritis pathogenesis." (PMID 41296710, 2025). "Serum BioLEP concentrations may be lower than LEP concentrations, depending on the degree of leptin resistance and the efficiency of its conversion in the bodies of children with obesity." (PMID 40586327, 2025). "In animal studies, a BP dose of 27 g/kg body weight (at a dose of 2.5% food) for 24 weeks (168 days) demonstrated anti-obesity and anti-diabetic properties in leptin-deficient (ob/ob) mice, without any evident toxic effects." (PMID 40699852, 2025). "Notably, mice in the HFD-IF group maintained elevated serum leptin levels postintervention, limiting the potential of IF to alleviate obesity-related infertility." (PMID 40292466, 2025). "Also, insulin serves a pivotal function in enhancing the activation of STAT3 mediated by leptin, which is a transcription factor of considerable importance within a crucial signaling pathway designed to inhibit the development of obesity." (PMID 40283443, 2025).
Obesity (continued). "Furthermore, several hormones produced by adipose tissue, including leptin, adiponectin and resistin, are dysregulated in obesity, further contributing to impaired bone health." (PMID 40468942, 2025). "Future studies could benefit from the integration of additional obesity‐related biomarkers, such as lipid profiles, fasting glucose, inflammatory markers (e.g., C‐reactive protein, interleukin‐6), and adipokines (e.g., leptin, adiponectin)." (PMID 40635463, 2025). "The leptin-based estimator reflects basal variations of satiety in women with obesity." (PMID 41036146, 2025). "However, in the context of obesity, the effectiveness of leptin in promoting fatty acid oxidation is diminished due to leptin resistance." (PMID 40016558, 2025). "Leptin, which is present at elevated levels in the circulation of individuals with obesity, plays a key role in modulating critical cellular processes in tumor cells, including proliferation, metastasis, apoptosis inhibition, angiogenesis, chemoresistance, and metabolic reprogramming." (PMID 40485730, 2025). "However, in metabolic disorders such as obesity, the adipo-insular axis is dysregulated, with chronically increased leptin levels contributing to the release of pro-inflammatory cytokines, leptin resistance, insulin resistance, and beta cell dysfunction." (PMID 40429752, 2025). "Serum Wnt5a, leptin, and TNF-α levels increase in women with obesity and the A allele of TLR2 (Arg753Gln) SNP could be protective against obesity-associated metaflammation." (PMID 39837875, 2025). "Other researchers have investigated the role of leptin on obesity and leptin in COVID-19 patients." (PMID 41359762, 2025). "Obesity, which is widespread in T2DM, is strongly associated with higher BMD, probably through mechanical loading and hormonal factors, including insulin, estrogen, and leptin." (PMID 40896277, 2025). "Obesity may predispose individuals to chronic kidney disease (CKD) directly through the production of adiponectin, leptin, and resistin, as well as its association with the histopathological features of obesity-related glomerulopathy." (PMID 41009007, 2025). "A growing body of evidence suggests that leptin may be a molecular link connecting obesity, psoriasis severity, and metabolic comorbidities." (PMID 40277935, 2025). "In addition, leptin and adiponectin levels are often imbalanced in obesity; leptin level is elevated, and adiponectin level is reduced, thereby contributing to chronic inflammation and insulin resistance." (PMID 40181294, 2025). "Absence of leptin or its receptor causes significant metabolic disorders such as obesity and type 2 diabetes." (PMID 41251447, 2025). "Leptin knockout mice (Ob/Ob) are hyperphagic, exhibit severe obesity with a high degree of adiposity, hypertrophied adipocytes, reduced testosterone levels, impairment of steroidogenic pathways, significant cellular changes in the germinal epithelium, and failures in spermatogenesis." (PMID 40195898, 2025). "In T21, decreased leptin levels may impair neuronal activity, potentially leading to obesity and related health complications in individuals with DS." (PMID 40489580, 2025). "However, other studies have noted elevated leptin levels in patients with psoriasis and coexisting obesity." (PMID 40095687, 2025). "However, among patients with severe obesity, plasma levels of leptin and adiponectin were higher in women than in men." (PMID 40943431, 2025). "A consequence may be disturbed leptin signaling and reduced satiety in children with overweight/obesity." (PMID 39899498, 2025). "In Chandigarh, India, next-generation sequencing in children with obesity identified one pathogenic variant in the MC4R gene, one likely pathogenic variant each in the LEPR, NTRK2, and LEP genes, as well as variants of uncertain significance in the POMC and LEPR genes." (PMID 40149731, 2025).
Obesity (continued). "Of particular interest, this protective association was significant only among individuals with BMI < 30 kg/m2, suggesting that central leptin resistance in obesity may impair these effects." (PMID 41516046, 2025). "Thus, obesity results from chronic hyperinsulinemia, which interferes with the leptin signal, at the VMH or VTA or both." (PMID 40950761, 2025). "These alterations may lead to leptin and insulin resistance, increased expression of orexigenic peptides like NPY and galanin, and a heightened risk of long-term obesity and hyperinsulinemia." (PMID 41374021, 2025). "Abnormal DNA methylations of key metabolic-related genes, such as Leptin, adiponectin, PGC1α, IGF-2, appetite-related genes-(POMC, NPY), are frequently implicated in the development of obesity and insulin resistance." (PMID 40702315, 2025). "Furthermore, obesity disrupts the balance of leptin and adiponectin, two key adipokines involved in energy homeostasis and insulin sensitivity." (PMID 40429763, 2025). "Increased levels of leptin and IGF-1 may serve as potential plasma biomarkers of elevated fetal adiposity, which can predispose individuals to infant obesity and metabolic dysfunction later in life." (PMID 40725173, 2025). "Further supporting this, SHBG overexpression in transgenic mice protects against high-fat (with carbohydrate) diet (HFD)-induced obesity and insulin resistance, improving glucose tolerance, lowering insulin levels, and attenuating increases in leptin and resistin levels." (PMID 41586225, 2025). "Furthermore, SYR helps to manage obesity by lowering body weight and fat mass, attenuating leptin levels, enhancing adiponectin circulation, improving insulin resistance, and modulating genes involved in lipid metabolism." (PMID 41170185, 2025). "The specific role of BBS1 in leptin signaling, which typically regulates appetite control and fat storage, may account for the observed higher rates of obesity in these patients." (PMID 40718228, 2025). "The unexpected association between low leptin levels and worse outcomes in patients with pulmonary embolism may be explained by the concept of the “obesity paradox”—a phenomenon suggesting that leptin’s role extends beyond merely reflecting body mass." (PMID 41226331, 2025). "However, in obesity (a common precursor to T2D), chronically elevated leptin levels lead to leptin resistance, impairing its regulatory effects and promoting further weight gain and IR." (PMID 40673471, 2025). "The present study aims to investigate the association of GHSR-1a immunopositive (+) cells from atherosclerotic plaque and PVAT with inflammatory markers (tissue concentrations of CRP, Il-6, leptin, and adiponectin) by studying the arteries harvested from patients with obesity and PAD." (PMID 40137085, 2025). "Leptin, a proinflammatory adipokine, is overproduced in obesity." (PMID 41267926, 2025). "The BMI-stratified analysis revealed significant differences in ESS, OSA indices (AI, HI, AHI), HbA1c, C-peptide, insulin, IGFBP4, and leptin levels in the obese group, consistent with obesity being an independent contributor to OSA severity and metabolic dysregulation." (PMID 41458545, 2025). "However, in obesity, despite elevated leptin levels, the body often becomes resistant to its effects, leading to disrupted appetite regulation and energy metabolism." (PMID 39897330, 2025). "Hence, obesity alone and type 2 diabetes with obesity were significantly associated with TNF-α, IL-6, leptin, adiponectin, resistin, and ALR even after adjusting for sex (Model 2) or age (Model 3)." (PMID 40095937, 2025). "In individuals with obesity, the dynamic equilibrium of lipid metabolism is disrupted, leading to excessive serum free fatty acids (FFAs), increased leptin, and decreased adiponectin levels, all of which can deteriorate insulin sensitivity and subsequently increase the risk of T2D." (PMID 41322468, 2025).
Obesity (continued). "While IRS2 deletion in LepRb neurons caused leptin resistance and obesity in mice, its ablation in POMC neurons did not significantly affect metabolic balance." (PMID 41251447, 2025). "In particular there is a high burden of metabolic disturbances, such as obesity, hyperphagia, and type 2 diabetes, due to the impaired leptin-melanocortin-4 receptor (MC4R) pathway that prevents appropriate activation of MC4R that is normally responsible for signaling hunger and satiety." (PMID 41048439, 2025). "However, in obesity, chronically elevated leptin levels induce SOCS1 and SOCS3, which in turn inhibit JAK2 phosphorylation and downstream STAT1/STAT2 activation." (PMID 40844207, 2025). "Due to the anorexigenic effect of leptin, H. pylori infection may stimulate overeating and contribute to obesity mechanisms." (PMID 40606632, 2025). "Low adiponectin levels and increased insulin resistance are also known to be associated with the clinical features of metabolic syndrome, as obesity and metabolic syndrome are characterized by decreased serum adiponectin levels in parallel with increased concentrations of circulating leptin." (PMID 40282897, 2025). "It is worth noting that, beyond SOCS3 and PTP1B, several additional molecules and cellular mechanisms have been implicated as negative regulators of LepRb signaling and may contribute to the development of leptin resistance in obesity." (PMID 41251447, 2025). "Furthermore, inosine treatment reversed obesity-induced hypothalamic leptin resistance and ameliorated obesity through the leptin pathway." (PMID 41016636, 2025). "It has also been determined that obesity, both in children and adults, induces a state of low-grade inflammation and metabolic alterations, such as increased plasma leptin, hyperinsulinemia, and elevated production of tumor necrosis factor-alpha (TNF-α) and interleukin-6 (IL-6), among others." (PMID 40531756, 2025). "However, obesity often leads to leptin resistance, a condition marked by inadequate leptin signaling despite high circulating leptin levels." (PMID 40636308, 2025). "Interventions aimed at disrupting leptin-EV pathways or modulating their downstream effects may offer novel strategies for potential therapeutic interventions for mitigating obesity-driven breast cancer aggressiveness." (PMID 40485730, 2025). "In contrast, adiponectin levels are reduced in obesity and counteract the effects of leptin." (PMID 40558305, 2025). "However, in the context of obesity, despite the increased production of leptin, the blood–brain barrier (BBB) permeability of leptin is reduced due to the onset of leptin resistance, while the production of adiponectin is reduced." (PMID 39861366, 2025). "For instance, hypothalamic leptin resistance disrupts energy homeostasis and promotes obesity and peripheral insulin resistance, and hippocampal leptin resistance may impair synaptic plasticity and memory formation while fostering amyloid-beta accumulation." (PMID 40619502, 2025). "Leptin is a component of human milk, and it is currently accepted that it contributes to the postnatal programming of a healthy adult phenotype, with a major role in obesity prevention." (PMID 39940412, 2025). "In children, obesity-induced hyperleptinemia and leptin resistance may have an even greater impact on synaptic plasticity of their developing brain, contributing to emotional and behavioural dysfunctions and cognitive deficits." (PMID 40607230, 2025). "It appears that dysregulated leptin secretion, as observed in obesity, may contribute not only to metabolic complications but also to hippocampal synaptic disturbances and an increased risk of cognitive impairment." (PMID 41464558, 2025). "The adipokine leptin exemplifies the complex link between obesity and VTE." (PMID 41226331, 2025).
Obesity (continued). "Partial reduction of circulating leptin in diet-induced obese (DIO) mice improved hypothalamic leptin sensitivity, prevented high-fat diet-induced obesity, and corrected glucose dysregulation, underscoring hyperleptinemia as both a driver and consequence of leptin resistance." (PMID 41516046, 2025). "Because of this occurrence, leptin resistance and obesity are prone to develop." (PMID 39822062, 2025). "Our results indicate that obesity has a negative impact on lipid profile and glycemic control in type 2 diabetes patients and highlight the significance of considering the effect of obesity on the relationship between leptin and lipid profile in diabetic patients." (PMID 41239622, 2025). "Obesity is a condition characterized by higher chemerin and leptin serum levels." (PMID 39887469, 2025). "Additionally, the ROC analysis demonstrated the ability of adipokines and VAI to discriminate obesity-related metabolic risk in PCOS patients, with leptin emerging as a particularly promising biomarker." (PMID 40792318, 2025). "When setting either the area or the perimeter of visceral adipocytes in participants with obesity as a dependent variable, a significant interaction was found, using the serum adiponectin/leptin ratio (R2 = 0.451, P = 0.009; R2 = 0.525, P = 0.003, respectively) as an independent variable." (PMID 41271970, 2025). "In human omental visceral AT (OVAT) samples from the Leipzig Obesity BioBank (LOBB, N = 52), LEP UE methylation was associated with body fat percentage, and mediation analysis indicated that leptin serum levels partially mediate this association exclusively in females." (PMID 39934931, 2025). "Obesity induces a state of chronic low-grade inflammation characterized by elevated adipokines (e.g., leptin) and proinflammatory cytokines (e.g., TNF-α and IL-6), which promote airway hyperreactivity, increase mucosal permeability, and amplify IgE-mediated responses to occupational allergens." (PMID 41154935, 2025). "High leptin levels found in obese people (in simple obesity) do not cause a decrease in appetite, which suggests leptin resistance." (PMID 40722842, 2025). "Adipokines such as leptin and adiponectin may also provide some cardioprotective reserves during critical illness, further contributing to this obesity paradox." (PMID 39860421, 2025). "It is plausible that, similar to its effects in tumors, leptin may increase VEGF production in obesity." (PMID 40900465, 2025). "Mechanistically, obesity promotes airway narrowing due to decreased lung volume, induces low-grade chronic pulmonary inflammation, and alters adipokine profiles (such as increased leptin), all of which contribute to asthma development and exacerbation." (PMID 40998975, 2025). "In contrast, the HIIT group exhibited a favorable hormonal profile characterized by reduced insulin and leptin levels (both typically elevated in obesity) and increased adiponectin concentrations, reflecting improved insulin sensitivity, leptin responsiveness, and adipose tissue function." (PMID 41367390, 2025). "An analysis of serum leptin concentrations showed a statistically significant difference between the three groups (p < 0.0001), being higher in the obesity group in relation to the overweight and eutrophic groups, and also higher in the overweight compared to the eutrophic group." (PMID 40359199, 2025). "In obesity, the normal operation of both ghrelin and leptin pathways is compromised." (PMID 41007669, 2025). "The fact that peak LH levels were lower as the degree of obesity increased, even though E2 levels remained unchanged, suggested mechanisms such as insulin and leptin resistance, decreased SHBG, and elevated androgen levels in obese individuals, independent of sex steroids." (PMID 40095159, 2025). "Additionally, elevated leptin levels in obesity promote local joint inflammation and cartilage matrix degradation, indicating leptin as a critical mediator linking obesity and OA." (PMID 40761349, 2025).